DES (desmin)
Diseases named in the same sentence as DES in open-access papers (continued):
Sharing a sentence is not in itself a finding about the gene and the disease.
mesothelioma (4 papers, 2016 to 2025). A usually malignant and aggressive neoplasm of the mesothelium which is often associated with exposure to asbestos. "Therefore, the author aimed to discover whether the observed cells were reactive mesothelial, mesothelioma, or adenocarcinoma cells via immunocytochemistry using five markers (cytokeratin, vimentin, desmin, E-cadherin, and calretinin)." (PMID 37480011, 2023). "Therefore, the author aimed to discover whether the observed cells were reactive mesothelial, mesothelioma, or adenocarcinoma cells through immunocytochemistry using five markers (cytokeratin, vimentin, desmin, E-cadherin, and calretinin) in a canine patient." (PMID 37480011, 2023). "Additionally, mesotheliomas generally show immunopositivity for CK5/6, CK7, and HBME-1 and are negative for desmin." (PMID 27403364, 2016).
myocarditis (4 papers, 2017 to 2026). Myocarditis is a condition that is characterized by inflammation of the heart muscle (myocardium). "Among patients with myocarditis, pathogenic or likely pathogenic variants in the desmin gene were more prevalent." (PMID 39858598, 2025). "Using A/J mice, a mouse strain susceptible to CVB3-induced myocarditis, we observed an abnormal accumulation of pre-amyloid oligomers in the myocardium of virus-infected heart, accompanied by disarrangement of desmin-associated cytoskeletal network." (PMID 29088822, 2017). "Among patients with myocarditis, pathogenic or likely pathogenic variants in the desmoplakin and desmin genes were of particular interest, as they distinguished this group from patients without myocarditis." (PMID 39858598, 2025).
nerve sheath tumors (4 papers, 2015 to 2025). "Immunohistochemistry for protein S-100, laminin, and desmin was performed to further characterize the lesion as a nerve sheath tumor." (PMID 41540823, 2025).
neurofibroma (4 papers, 2018 to 2025). An intraneural or extraneural neoplasm arising from nerve tissues and neural sheaths. "Immunohistochemical staining was positive for S-100 but negative for c-KIT, CD34, α-SMA, and desmin, and these morphologic and immunohistochemical characteristics were consistent with a diagnosis of neurofibroma." (PMID 30178113, 2018). "Immunohistochemical staining was positive for S-100 but negative for c-KIT, CD34, α-SMA, and desmin; these morphological and immunohistochemical characteristics were consistent with the diagnosis of neurofibroma." (PMID 30178113, 2018).
nodular fasciitis (4 papers, 2019 to 2024). A self-limiting, rapidly growing, non-encapsulated benign neoplasm that arises from the soft tissues. "However, the immunohistochemistry for both nodular fasciitis and JFO may show positivity for vimentin, smooth muscle actin (SMA), and desmin." (PMID 39712824, 2024). "Tendon sheath fibroma should also be distinguished from nodular fasciitis, because tendon sheath fibromas share most of the immunohistochemical markers with nodular fasciitis, such as positive vimentin, smooth muscle actin and negative desmin." (PMID 30611237, 2019).
pulmonary fibrosis (4 papers, 2019 to 2024). Chronic progressive interstitial lung disorder characterized by the replacement of the lung tissue by connective tissue, leading to progressive dyspnea, respiratory failure, or right heart failure. "In the final step, we therefore investigated the association of collagen and desmin marker expression with each of those cell populations in murine pulmonary fibrosis models." (PMID 32023084, 2020). "Moreover, an immunohistochemical study of human pulmonary fibrosis revealed that myofibroblasts express SMA, vimentin, and desmin." (PMID 32807166, 2020).
spindle cell lipoma (4 papers, 2005 to 2018). A benign circumscribed tumor composed of spindled cells, adipocytes, and collagen bundles. "In addition, mammary-type myofibroblastoma shows desmin positivity on immunohistochemistry, while spindle cell lipoma does not." (PMID 30567070, 2018). "Spindle cell lipoma does not show any positivity for smooth-muscle actin, desmin or vimentin." (PMID 16281980, 2005).
adenoma (3 papers, 2012 to 2017). A neoplasm arising from the epithelium. "We analyzed expression of αSMA and desmin in normal human oviducts and oviductal adenomas to study changes in the stromal compartment and found that expression of these markers was limited to the blood vessels and very little staining was observed in the stromal cells." (PMID 22916036, 2012).
adrenal cortical carcinoma (3 papers, 2019 to 2023). "One of these components stained positively for calretinin and inhibin, which is indicative of adrenal cortical carcinoma; the other exhibited strong expression of vimentin and desmin, which was concordant with sarcomatous change and confirmed the diagnosis of adrenal cortical carcinosarcoma." (PMID 36292108, 2022).
Astrocytoma (3 papers, 2016 to 2024). "Astrocytoma cells react strongly with GFAP and negatively with synaptophysin, neurofilament, desmin, cytokeratin, and epithelial membrane antibodies." (PMID 27568373, 2016).
cataract (3 papers, 2009 to 2024). Partial or complete opacity of the crystalline lens of one or both eyes that decreases visual acuity and eventually results in blindness. "An autosomal dominant missense mutation in αB-crystallin (αB-R120G) causes cataracts and desmin-related myopathy, but the underlying mechanisms are unknown." (PMID 21445271, 2011).
chondrosarcoma (3 papers, 2010 to 2023). A malignant cartilaginous matrix-producing mesenchymal neoplasm arising from the bone and soft tissue. "Compared with chondrosarcoma, chondroma is more differentiated and less likely to have binucleated cells; chordoma is more likely to immunohistochemically express CK and EMA; chondromyxoid fibroma is positive for S100, and positive to desmin and CD34 to varying degrees." (PMID 37669996, 2023).
clear cell sarcoma (3 papers, 2021 to 2025). A rare malignant neoplasm with melanocytic differentiation characterized by the presence of polygonal or spindle shaped clear cells. "Additional diagnostics such as immunohistochemical staining for the presence of cytokeratin, vimentin, desmin, actin, and WT1 allows distinguishing between other rare cancer types such as renal sarcoma, mesoblastic nephroma, clear cell sarcoma, or rhabdoid tumor." (PMID 34322362, 2021).
cutaneous melanoma (3 papers, 2018 to 2024). A primary melanoma arising from atypical melanocytes in the skin. "All excised tumors were diagnosed as primary cutaneous melanomas with rhabdoid differentiation based on histomorphological findings and immunohistochemistry considering S100, MART-1, SOX-10, HMB-45, vimentin and desmin." (PMID 35645230, 2022). "To explore whether pericytes contribute to VM, we stained a series of primary human cutaneous melanoma tissues, a tumor type that is known to frequently display VM, using different pericyte markers, i.e. α‐smooth muscle actin (αSMA), neural/glial antigen 2 (NG2), and desmin." (PMID 30101525, 2018).
dendritic cell tumor (3 papers, 2010 to 2021). A dendritic cell tumor develops from the cells of the immune system. "FRCT has a similar histomorphology to other dendritic cell tumors with a rather distinct immunophenotype including expression of SMA, desmin, and CD68 as well as cytokeratin, which separates it from the others." (PMID 34514557, 2021). "FDCS typically lacks expression of CD1a, desmin and CD45, which allows their differential diagnosis with interdigitating dendritic cell tumors, Langherhans cell tumors, histiocytic and lymphoid neoplasias." (PMID 20937101, 2010).
epithelioid leiomyoma (3 papers, 2021 to 2025). "Strong positive staining for desmin and SMA favored the diagnosis of epithelioid leiomyoma." (PMID 40861708, 2025). "Furthermore, in our case the tumour cells were negative for desmin, excluding and epithelioid leiomyoma." (PMID 34508517, 2021).
fibroma (3 papers, 2020 to 2022). A non-metastasizing neoplasm arising from the fibrous tissue. "In addition, there is no expression of SMA, HHF35 or desmin in non-ossifying fibroma tissue, which aided in making the diagnosis." (PMID 36611301, 2022).
fibrous tumor (3 papers, 2022 to 2024). "Solitary fibrous tumors have a haphazard arrangement of spindled to ovoid cells arranged around branching and dilated vasculature within a variably collagenous stroma; desmin is expressed by a subset of cases while STAT6 positivity is typical." (PMID 36579603, 2022). "Immunohistochemical stains for pan-cytokeratin, DOG1, desmin, S100, CD34, and MUC4 were negative, and a diagnosis of the calcifying fibrous tumor was rendered." (PMID 36186113, 2022).
granular cell tumor (3 papers, 2013 to 2025). An unusual benign or malignant neoplasm characterized by the presence of neoplastic large polygonal cells with granular, eosinophilic cytoplasm which contains abundant lysosomes. "Granular cell tumors show diffuse S-100 positivity and desmin negativity." (PMID 24288631, 2013).
hepatocellular carcinoma (3 papers, 2014 to 2020). A malignant tumor that arises from hepatocytes. "Furthermore, it has been shown that TGFβ1 up-regulates miR-155 in hepatocellular carcinoma cells, thus promoting epithelium-to-mesenchyme transition, invasion and metastasis, and that miR-155 plays a role in mediating TGFβ1-induced podocyte injury via nephrin, desmin and caspase-9." (PMID 29987196, 2018). "While in the desmoplastic component of hepatocellular carcinomas and pancreatic ductal adenocarcinomas there is a significant contribution of desmin + stellate cells, this is not the case in colon adenocarcinomas." (PMID 25417197, 2014).
laminopathies (3 papers, 2019 to 2023). "Interestingly, ameliorating the desmin-associated defects in these cardiomyocytes provided cardioprotection from the H222P lamin A/C mutation, suggesting that desmin is a promising target for certain laminopathies." (PMID 36960155, 2023).
Lipoleiomyomas (3 papers, 2021 to 2025). "Lipoleiomyomas typically express smooth muscle markers such as desmin and h-caldesmon in the smooth muscle component, and S100 protein in the adipocytic component." (PMID 40625645, 2025). "While cross-sectional imaging can narrow the differential diagnosis, histopathological analysis with stains positive for smooth muscle actin, desmin, and estrogen receptor, but negative for HMB-45 confirms the diagnosis of lipoleiomyoma." (PMID 33964957, 2021).
lung carcinoma (3 papers, 2021 to 2025). "In lung cancer, desmin-positive CAFs recruit TAMs by secreting IL-8 and promote M2 polarization of TAMs, thereby changing the composition of the TME and promoting the progression of lung cancer." (PMID 40453088, 2025).
metastatic disease (3 papers, 2022 to 2025). "Using ASCD analysis, all four RMS patients with metastatic disease had at least one CTC (median 14.5, range 1–643), and the majority expressed desmin (median 94.8%, range: 8.3–100%)." (PMID 35212153, 2022).
myotilinopathy (3 papers, 2015 to 2019). "Our findings in myotilinopathy presented in this work indicate that Z-disc-associated proteins, especially filamin C, desmin and their binding partners, are the most abundant components of the pathological aggregates in muscle fibers of myotilinopathy patients." (PMID 26842778, 2016).
Obesity (3 papers, 2018 to 2023). Accumulation of substantial excess body fat. "Using this obesity mouse model, we found that the expression levels of both DNase2 and TREX1 in HSCs (which express Desmin) were substantially reduced in obese mice fed a high-fat diet (HFD), as compared to those in lean mice fed a normal diet (ND)." (PMID 29593264, 2018).
primitive neuroectodermal tumor (3 papers, 2009 to 2023). A malignant neoplasm that originates in the neuroectoderm. "Immunohistochemistry showed diffuse strong membrane positivity for MIC2, focal positivity for synaptophysin and negativity for desmin and diagnosis came compatible with ES or primitive neuroectodermal tumor (PNET)." (PMID 25206203, 2013).
renal fibrosis (3 papers, 2018 to 2024). A final common manifestation of a wide variety of chronic kidney diseases characterized by glomerulosclerosis and tubulointerstitial fibrosis. "This study found that HG-induced podocyte EMT in diabetic kidneys is characterized by increased expressions of mesenchymal α-SMA and desmin and decreased expressions of nephrin and podocin, contributing to renal fibrosis." (PMID 37638046, 2023). "Moreover, this agent downregulates the mesenchymal marker desmin in podocytes and blocks transforming growth factor—beta autoinduction, leading to attenuation of renal fibrosis in a unilateral ureteral obstructive (UUO) model." (PMID 29270765, 2018).
rhabdoid tumor (3 papers, 2021 to 2025). An aggressive malignant embryonal neoplasm usually occurring during childhood. "Rhabdoid tumors of different cell lineages are often positive for the mesenchymal markers vimentin and desmin." (PMID 35645230, 2022). "In general, most rhabdoid tumors stain positive for the mesenchymal markers vimentin and/or desmin." (PMID 35645230, 2022).
spindle cell rhabdomyosarcoma (3 papers, 2021 to 2022). An uncommon variant of rhabdomyosarcoma characterized by the presence of whorls of spindle cells forming a storiform pattern. "And strongly positive for desmin and MyoD1 in the spindle cell rhabdomyosarcoma case." (PMID 36173721, 2022). "Immunohistochemical analysis showed negative staining with Cytokeratin, S100, CD34, Stat6, h-Caldesmon and EMA while the tumour cells were positive for desmin, myogenin, smooth muscle actin, CD-99 and MyoD1 thus confirming the diagnosis of spindle cell rhabdomyosarcoma." (PMID 34104191, 2021). "Positivity for epithelial antibody markers and negative staining for skeletal muscle-specific markers, namely desmin, myogenin and MyoD1, ruled out a spindle cell rhabdomyosarcoma." (PMID 34514569, 2022).
teratoma (3 papers, 2016 to 2025). A non-seminomatous germ cell tumor characterized by the presence of various tissues which correspond to the different germinal layers (endoderm, mesoderm, and ectoderm). "The immunohistochemical findings in this case demonstrated positive staining for mesodermal markers, such as desmin and SMA, along with the embryonic stem cell marker OCT4/POU5F1, confirming the diagnosis of a mature teratoma." (PMID 40657604, 2025). "Three tumors stained for Placental alkaline phosphatase (PLAP, a marker of reproductive system tumors), cytokeratin (CK, a marker for tumor cells of epithelial origin), desmin (DES, a marker of myogenic origin tumor or tissue), and α-fetoprotein (AFP, marker of teratoma)." (PMID 28103575, 2017).
undifferentiated carcinoma (3 papers, 2012 to 2025). A usually aggressive malignant epithelial neoplasm composed of atypical cells which do not display evidence of glandular, squamous, or transitional cell differentiation. "No significant expression of Desmin or S-100 was detected in both mucinous and undifferentiated carcinoma, consistent with the expression pattern of dedifferentiated carcinoma." (PMID 40427213, 2025).
Uterine leiomyoma (3 papers, 2010 to 2022). The presence of a leiomyoma of the uterus. "Immunohistochemical staining was positive for smooth muscle α-actin and desmin, as well as estrogen and progesterone receptors, consistent with the diagnosis of uterine leiomyoma." (PMID 29951323, 2018). "The human uterine leiomyoma (UtLM) cells were positive for both desmin (center) and vimentin (upper left)." (PMID 20537183, 2010). "In addition, immunohistochemical analysis showed that the SMA and desmin positive rates were both 100%, suggesting that IVL has molecular cytogenetic characteristics similar to those of uterine leiomyoma." (PMID 36793517, 2022).
uterine tumor (3 papers, 2014 to 2017). "Both oviductal and uterine tumor cells were positive for cytokeratin 8, an epithelial marker, and negative for desmin, a stromal cell marker, confirming the epithelial origin of these tumors." (PMID 25078979, 2014). "The diagnosis of pulmonary metastases was obtained by reviewing the histology of the previous uterine tumor: the tumor cells were immunoreactive for CD10, PR, and smooth muscle actin (SMA), but negative for desmin, S100, CD34, CD 117, cytokeratins AE1AE3, CD68R, and ER." (PMID 24744931, 2014).
adenomyoma (2 papers, 2012 to 2022). A benign neoplasm characterized by the presence of a glandular and a mesenchymal (fibromyomatous) component. "In contrast, αSMA and desmin staining is increased in the stroma of the oviductal adenomyomas (N = 8/10), suggesting of expansion of myofibroblast/smooth muscle cell population." (PMID 22916036, 2012).
adrenal carcinoma (2 papers, 2019 to 2023). A carcinoma involving a adrenal gland. "Therefore, we next assessed the organization of desmin wt and C333S constructs in the adrenal carcinoma cell line SW13/cl.2, which lacks a cytoplasmic intermediate filament network." (PMID 37760006, 2023). "SW13 cells are an adrenal carcinoma cell line that lacks type III IFs such as vimentin and desmin, allowing one to evaluate newly synthesized IF formation." (PMID 31371504, 2019).
angioma (2 papers, 2024 to 2026). "Immunohistochemical results-SMA(+), D2-40(focal +), CD31(+), CD34(+), Desmin(+), and HMB45(-)-confirmed angioma." (PMID 42238270, 2026). "H&E showed hemangiomas with (CD34+, CD31+, anti-desmin negative) no cellular atypia." (PMID 39364018, 2024).
atherosclerosis (2 papers, 2021 to 2024). A disease characterized by the build-up of fatty material and calcium deposition in the arterial wall resulting in partial or complete occlusion of the arterial lumen. "In addition, the yeast two-hybrid assay indicated that desmin’s head domain also interacts with aldehyde dehydrogenase 4 family member A1 (ALDH4A1) (clone-132), which is a mitochondrial enzyme involved in proline metabolism and is related to atherosclerosis." (PMID 38607042, 2024).
atrial fibrillation (2 papers, 2022 to 2025). A disorder characterized by an electrocardiographic finding of a supraventricular arrhythmia characterized by the replacement of consistent P waves by rapid oscillations or fibrillatory waves that vary in size, shape and timing and are accompanied by an irregular ventricular response. "Additionally, desmin deficiency causes cytosolic calcium overload and reduced sarcoplasmic reticulum calcium, which increases the risk of atrial fibrillation." (PMID 40529556, 2025).
brain tumor (2 papers, 2016 to 2024). "The altered BBB permeability in brain tumor lesions is referred to as the brain tumor barrier (BTB) and has been associated with a high expression of the pericyte marker, desmin, and lower collagen-IV content in the EC basement membrane." (PMID 38473273, 2024). "Nuclear transport and presence of IF proteins has been demonstrated for tail-less cytokeratin 8, 18, and 19 in 3T3 fibroblasts, for vimentin in nasopharyngeal carcinoma lymph node metastasis, for nestin in various brain tumors, and for desmin in BHK21 cells." (PMID 26787680, 2016). "Desmin has been detected in nuclei of BHK21 cells and nestin in nuclei of brain tumor cells." (PMID 26787680, 2016).
colorectal tumor (2 papers, 2011 to 2023). "In our 2D DIGE study, desmin was found over-expressed in colorectal tumors relative to matched normal mucosa." (PMID 22141345, 2011). "In other proteomic studies desmin was not identified among proteins over-expressed in colorectal tumors." (PMID 22141345, 2011).
congestive heart failure (2 papers, 2011 to 2015). Failure of the heart to pump a sufficient amount of blood to meet the needs of the body tissues, resulting in tissue congestion and edema. "Another study involving human hearts suffering from congestive heart failure identified, by western blot, an increase of desmin protein expression." (PMID 25889944, 2015).